IGFBP4 (insulin like growth factor binding protein 4)
Diseases named in the same sentence as IGFBP4 in open-access papers (continued):
Sharing a sentence is not in itself a finding about the gene and the disease.
steatosis (1 paper, 2023). Increased lipid within the cytoplasm of cells. "Analyses of these proteins showed a negative correlation between IGFBP2, IGFBP4, and steatosis grade (r = −0.49, p < 0.02; r = −0.12, p < 0.02), while IGFBP6 and IGFBP7 were positively associated with steatosis (r = 0.25, p < 0.005; r = 0.35, p < 0.0001)." (PMID 36831184, 2023).
systemic sclerosis (1 paper, 2022). A chronic disorder, possibly autoimmune, marked by excessive production of collagen which results in hardening and thickening of body tissues. "Another study found that IGFBP-4 has an antifibrotic role in systemic sclerosis, a prototypic fibrotic disorder, through reducing TGFβ-induced ECM production and the expression of the profibrotic factor CTGF." (PMID 35356065, 2022).
triple-negative breast carcinoma (1 paper, 2023). An invasive breast carcinoma which is negative for expression of estrogen receptor (ER), progesterone receptor (PR), and human epidermal growth factor receptor 2 (HER2). "Meanwhile, the expression of MEX3A and IGFBP4 correlated with triple-negative breast cancer (TNBC) of the lack of estrogen and progesterone receptors and HER2." (PMID 37433992, 2023).
yang deficiency (1 paper, 2022). Yang deficiency is a concept from traditional Chinese medicine. "Considering the different regulated expression levels, ADIPOQ, MBL2, and IGFBP4 might be potential biomarkers for differentiation and identification of Yang deficiency and Qi-yin deficiency syndromes of HF." (PMID 35087594, 2022). "In addition, several disease related proteins were exclusively involved in the PPI network of the Yang deficiency group, such as adiponectin receptor protein 1 (ADIPOQ), mannose-binding protein C (MBL2), and insulin-like growth factor-binding protein 4 (IGFBP4)." (PMID 35087594, 2022).
tumor (76 papers, 2007 to 2026). "In the present study, we performed loss-of-function experiments and found that IGFBP4 effectually reversed tumor inhibition caused by MEX3A depletion." (PMID 37433992, 2023). "On the other hand, an IGF-independent mechanism is associated with the IGFBP-4 regulation of tumor growth by means of the modulation of estrogen receptor α activation." (PMID 37298551, 2023). "Loss of the IGFBP4 tumor suppressor drives H3K27me3-mediated epigenetic reprogramming in hepatic carcinogenesis." (PMID 36575438, 2022). "Of particular interest is the behavior of IGFBP-4; this cytokine is known to cause an increase in apoptosis and Bax protein expression, and a decrease in tumor cellular mitosis." (PMID 28316601, 2017). "In addition, osteopontin (OPN) and IGFBP-4 have been linked to chemoresistance, survival prediction, and tumor progression, whereas cystatin C has gained attention for its role in regulating protease activity and promoting metastasis." (PMID 41149076, 2025). "In addition, overexpression of FGFR1 and IGFBP4 genes was found significantly associated with early tumor stage (i.e., tumor stage < = 2)." (PMID 34061869, 2021). "Increased tumor growth in PAPPA secreting cell lines could result from the enhanced IGF signaling caused by degradation of IGFBP4 and thus increases in the bioavailability of IGFs." (PMID 23152806, 2012). "PAPP-A is a metalloproteinase with IGFBP-4 proteolytic activity now demonstrated in breast, ovarian, lung, smooth muscle, bone, kidney, thymus, adipose, cardiovascular and immune cells; and its deletion has been implicated in promoting longevity and reducing tumor burden." (PMID 38395880, 2024). "In the context of angiogenesis and tumor growth, Igfbp4 gene expression was upregulated in response to hypoxia, which substantiates the role of Igfbp4 as a hypoxia-regulated gene with a potential role in controlling tumor growth." (PMID 40806552, 2025). "It is generally accepted that IGFBP4 inhibits tumor development and progression by sequestering IGFs." (PMID 37349627, 2024). "IHC further demonstrated that miR-122-5p lentivirus treatment increased the expression of miR-122-5p and IGFBP4 in the tumor, suggesting that miR-122-5p can also promote the expression of IGFBP4 in vivo." (PMID 37349627, 2024). "The epigenetic suppression of IGFBP-4 is suggested to positively affect tumor development by reducing IGF inhibition." (PMID 37298551, 2023). "As the most prevalent IGFBP in circulation, IGFBP4 has been reported to serve a crucial role in tumor development regulation by inhibiting IGF activities." (PMID 37664853, 2023). "The newly discovered crucial roles of MEX3A and IGFBP4 in tumor progression provide theoretical basis of pathogenesis and potential novel strategy for the treatment of BC." (PMID 37433992, 2023). "qPCR results showed that Pappa, Igf1 and Stc1 were only expressed in the CAFs, while Igf1r, Stc2 and Igfbp4 were expressed in both tumor cells and CAFs." (PMID 35205651, 2022). "Spearman’s correlation test showed that IGFBP4 were significantly correlated with the tumor metastasis (ρ = − 0.843, P < 0.001), enneking stage (ρ = − 0.500, P < 0.001), and TAGLN (ρ = 0.821, P < 0.001)." (PMID 35665757, 2022). "Ectopic expression of the lncRNAs-IGFBP4 produced opposite results which we believe that normally, it is upregulated in the cancer cells and tissues showing low autophagy and high tumor progression." (PMID 36072894, 2022). "IGF1 was also expressed in the CAFs while IGFR1 was predominantly expressed in the tumor cells: STC1, STC2 and IGFBP4 were expressed in both tumor cells and CAFs." (PMID 35205651, 2022). "Spearman’s correlation coefficient displayed that IGFBP4 were significantly correlated with the tumor metastasis (ρ = − 0.843, P < 0.001), enneking stage (ρ = − 0.500, P < 0.001), and TAGLN (ρ = 0.821, P < 0.001)." (PMID 35665757, 2022).
tumor (continued). "In the individuals, pathologic grade (P = 0.017), tumor metastasis (P < 0.001), and enneking stage (P < 0.001) were significantly correlated with IGFBP4." (PMID 35665757, 2022). "In recent years, studies have shown that IGFBP4 can play an essential role in regulating the growth of various tumor cells through IGFs-dependent or IGFs-independent mechanisms." (PMID 35665757, 2022). "The results showed that pathologic grade (P = 0.017), tumor metastasis (P < 0.001), and enneking stage (P < 0.001) were significantly correlated with IGFBP4." (PMID 35665757, 2022). "Our ‘in-house’ RNAseq data demonstrate that increased PLEKHS1 expression is significantly associated with high-risk NMIBC (in both G3T1 tumours and CIS) and significant reductions in the expression of IGFBP-2, IGFBP-4, and IGF-1R." (PMID 34681810, 2021). "Although IGFBP-4 has been proposed to regulate tumour growth by affecting malignant progression and inhibiting colony formation, the mechanisms involved in these IGF-independent functions have not been fully elucidated." (PMID 34177367, 2021). "In lung adenocarcinoma cells, the expression of IGFBP-4 is epigenetically silenced through hypermethylation of its promoter, resulting in increased tumor proliferation and disruption of the mediated growth inhibition." (PMID 34298698, 2021). "We also noted that some proliferation-associated genes in tumor cells were also significantly regulated by CRNDE knockdown, including IGFBP4, ANXA1, KLF6, AATF, and IFI16." (PMID 33298855, 2020). "A PAPP-A resistant IGFBP4, dBP4, inhibits angiogenesis and metastasis in 4T1.2 mammary fat pad tumours." (PMID 30348128, 2018). "RT-qPCR performed was to exam the expression of IGFBP4 expression in 159 LC tissues compared with adjacent non-tumor tissues." (PMID 28946875, 2017). "To evaluate the effect of lnc-IGFBP4–1 on lung carcinogenesis in vivo, we established xenograft tumor models in nude mice with PC-9 cells transfected with overexpression-lnc-IGFBP4–1 treatment." (PMID 28946875, 2017). "Recent studies have reported IGFBP-4 is found to inhibit tumour progression via sequestering IGFs and cancer inhibitory effects of IGFBP-4 are generally accepted." (PMID 28946875, 2017). "In contrast, IGFBP5 tumor tissue levels have been found to be significantly associated with poor disease outcome and the addition of IGFBP4 (measured as IGFBP5/IGFBP4 ratio expression levels) further increased prognostic power." (PMID 25743390, 2015). "Analysis of xenograft tumor tissue recovered from treated mice showed penetration of mAb 1/41, reduced IGFBP-4 proteolysis, and reduced AKT phosphorylation." (PMID 24572990, 2014). "In line with our findings, a recent report showed the inhibition of tumor growth by expressing a protease-resistant IGFBP4 form." (PMID 24962328, 2014). "In TβRII KO tumor epithelium compared with TβRIIfl/fl epithelium, Igfbp4 and Tspan13 expression was upregulated while Col1α2, Bmp7, Gng11, Vcan, Tmeff1, and Dsc2 expression was downregulated." (PMID 22748014, 2012). "Insulin-like growth factor binding protein (IGFBP-4) was consistently present in the top 7.5% of all expressed genes in all tumor samples." (PMID 22264331, 2012). "Serum levels were tested during chemotherapeutic regimens in order to monitor the correlation between tumor status and IGFBP-4 levels." (PMID 22264331, 2012). "IGFBP4 expression in normal mammary fat pad tissue and 4T1.2 mammary fat pad tumours was then examined." (PMID 19536088, 2009). "There were almost no apoptotic endothelial cells in control tumours or those expressing wild-type IGFBP4, but there were large numbers of apoptotic endothelial cells in the tumours expressing protease-resistant IGFBP4." (PMID 19536088, 2009). "Tumours expressing protease-resistant IGFBP4 grew significantly more slowly than tumours transfected with pCMV or pCMV-BP4 (measured as time to reach an MTD of 17 mm)." (PMID 19536088, 2009).
tumor (continued). "Our data clearly show that expression of PAPP-A-resistant IGFBP4 results in endothelial cell apoptosis within the tumours and inhibition of tumour growth." (PMID 19536088, 2009). "As PAPP-A is expressed by fibroblasts and osteoblasts, host cells in and around tumours are likely to play an important role in proteolysis of IGFBP4." (PMID 19536088, 2009). "The in vitro data suggested that IGFBP4 would inhibit IGF1-stimulated growth of 4T1.2 tumours by blocking its effects on tumour cell and endothelial cell proliferation and VEGF production." (PMID 19536088, 2009). "4T1.2 tumours expressing dBP4 grew significantly more slowly than controls or tumours expressing wild-type IGFBP4." (PMID 19536088, 2009). "Tumours expressing PAPP-A-resistant IGFBP4 (C) had significantly higher numbers of apoptotic endothelial cells (6.97±3.26 s.e.m/h.p.f)." (PMID 19536088, 2009). "Within the tumour environment, it is likely that the secretion of IGFBP4 in the presence of the IGFBP4 protease (produced by host cells, such as fibroblasts and osteoblasts) provides a steady supply of IGF1 to the tumour to support its growth and angiogenesis." (PMID 19536088, 2009). "The effect was assessed 4 weeks later by evaluating the tumours for mitosis, necrosis, apoptosis, and expressions of IGFBP-4, Bcl-2 and Bax proteins." (PMID 17988381, 2007). "In our previous studies, we found that overexpression of IGFBP-4 on established subcutaneous cancer model can increase tumour apoptosis and decrease tumour cellular mitosis." (PMID 17988381, 2007). "The effect of IGFBP-4 on cancer initiation and development was then assessed by examining tumour volume, tumour histology, tumour cellular apoptosis and some proteins expression." (PMID 17988381, 2007). "Western blot and densitometry analysis showed a decreased expression of IGFBP-4 by tumours of both BP-4 and control M groups and an increased expression by Control P group (0.63 ± 0.03 vs 0.75 ± 0.09 vs1.04 ± 0.06, BP-4 vs control M vs Control P, P = 0.002)." (PMID 17988381, 2007). "CLEC14a, EMCN, and ADM5 were further validated in the single-cell Curated Cancer Cell Atlas (3CA) to be highly specific to the endothelial cell clusters across multiple tumor types, while IGFBP4 was diversely expressed in endothelial, fibroblast, and some malignant cell types." (PMID 41776551, 2026). "Protein–protein interaction analysis suggested that IGFBP4 is associated with IGF1, IGF2, and extracellular matrix associated proteins such as COL4A2, which was a significant factor affecting tumor metastasis and implying that IGFBP4 affects cell invasion through the IGF signaling pathway." (PMID 37349627, 2024). "Notably, our analysis of data from Fudan University revealed that high IGFBP4 expression was a protective factor for tumor chemotherapy, implying that IGFBP4 can be used to guide postoperative chemotherapy." (PMID 37349627, 2024). "Overall, the existing literature suggests that IGFBP4 can inhibit tumor progression." (PMID 37349627, 2024). "In conclusion, our study demonstrated that MEX3A, a novel carcinogenic RBP in BC, could promote tumor cell progression through mediated IGFBP4 post-transcriptional metabolism, ultimately affecting survival in BC patients." (PMID 37433992, 2023). "Remarkably, tumor growth was reduced by 60% in the experimental IGFBP-4-treated animal model." (PMID 37398678, 2023). "Modulation of IGFBP4 expression has previously been suggested as a therapeutic strategy, with a degradation-resistant form of the protein demonstrating significant effects on tumour growth and angiogenesis in both in vitro and in vivo models." (PMID 35834073, 2022). "IGFBP-4 plays an important role in tumor growth regulation by inhibiting IGF actions." (PMID 35741697, 2022). "IGFBP4 is the smallest member of human insulin-like growth factors binding proteins (IGFBPs), which is involved in the inhibition of oncogenic pathways and exerts a powerful tumor suppressor function in HCC cells." (PMID 35646665, 2022).
tumor (continued). "The inhibitory effects of IGFBP-4 on IGF have also been observed in tumour cells." (PMID 34177367, 2021). "In contrast, IGFBP-4 is involved in tumour growth regulation by inhibiting the activities of IGFs." (PMID 34177367, 2021). "In addition to the well-known IGF-related roles of IGFBP-4, it regulates tumour growth through IGFindependent mechanisms." (PMID 34177367, 2021). "Strikingly, for genes in cluster ii), which are specifically up-regulated in AAS, high expression of 7 of the top 10 genes (C3, CD74, HLA-DRA, STRA6, IGFBP4, PIGR, and TNIP1) was strongly associated with better cumulative survival than tumours with low expression of these genes." (PMID 32218455, 2020). "In addition, there was increased endothelial cell apoptosis within 4T1.2 tumours expressing dBP4 relative to tumours expressing wild type IGFBP4 or transfected with empty vector." (PMID 30348128, 2018). "We might speculate that the overexpression of IGFBP4 in R and LR xenografts by inducing senescence or breaking the cell cycle in tumor cells might enable them to counteract cDDP activity." (PMID 26910918, 2017). "Taken together, these findings suggest that lnc-IGFBP4–1 could function as a tumor promoter via regulating cell growth and inhibit apoptosis, and could be as a new biomarker for LC." (PMID 28946875, 2017). "We found that overexpression of lnc-IGFBP4–1 in cancerous cells notably promoted tumor growth and metastasis both in vivo and in vitro, while downregulation of endogenous lnc-IGFBP4–1 could inhibited cell proliferation and induce apoptosis." (PMID 28946875, 2017). "In addition, xenograft tumor models showed overexpression of lnc-IGFBP4–1treatment resulted in bigger tumor volume." (PMID 28946875, 2017). "The tumor volume in the overexpressed lnc-IGFBP4–1treatment group was significantly increase compared to that in the control group, and tumor volume was 636 ± 64.1 mm3, which was significantly bigger than that in control group (441 ± 58.5 mm3) on the day 24 (P < 0.05)." (PMID 28946875, 2017). "IGFBP-4 is found to inhibit tumour progression by sequestering IGFs, but some reports demonstrate that, in some circumstances, it might suppress cell death or stimulate cell migration." (PMID 25866791, 2015). "The ability of tumor extracts to proteolyze IGFBP-4 was then assessed." (PMID 24572990, 2014). "IGFBP-4 ranked among the top 7.5% (average top 3%) of expressed genes across all tumor samples." (PMID 22264331, 2012). "Our hypothesis was that IGFBP-4 levels may provide insight into tumor behaviour, ie resistance or recurrence." (PMID 22264331, 2012). "Second, IGFBP-4 levels are significantly elevated with malignant versus benign disease." (PMID 22264331, 2012). "We hypothesised that a protease-resistant IGFBP4, however, would inhibit 4T1.2 tumour growth by binding IGF1 rendering it biologically inactive even in the presence of PAPP-A." (PMID 19536088, 2009). "Therefore, in the mammary tissue at least, the interaction between the tumour cells and associated host cells is important for PAPP-A-mediated cleavage of IGFBP4 and therefore control of IGF bioavailability and activity." (PMID 19536088, 2009). "Median IGFBP-4 tumor expression was significantly greater in primary versus metastatic patients (70% versus 10%, p = 0.01) A trend for greater median IGFBP-3 sera concentration was observed in metastatic versus primary patients (4.9 μg/ml vs. 3.4 μg/ml, respectively, p = 0.09)." (PMID 19025658, 2008). "The expression of IGFBP-4 was higher in tumours of control P group than other two groups." (PMID 17988381, 2007). "TUNEL assay demonstrated an increase in apoptotic index by the tumours after IGFBP-4 gene therapy." (PMID 17988381, 2007). "Our observation that knocking down H19 upregulates IGFBP4, which counteracts the tumor promoting activity of IGF2, could provide a link in trans between H19 and IGF2." (PMID 17786216, 2007).